SFXN5 (sideroflexin 5)
Description:
Mitochondrial amino-acid transporter (By similarity). Transports citrate (By similarity). Does not act as a serine transporter: not able to mediate transport of serine into mitochondria (By similarity). In brown adipose tissue, plays a role in the regulation of UCP1-dependent thermogenesis probably by supporting mitochondrial glycerol-3-phosphate utilization (By similarity).
Synonyms: BBG-TCC; SLC56A5
Tractability: Antibody: UniProt predicts a signal peptide or a membrane-spanning region. PROTAC: ubiquitination databases record sites on it; its protein half-life has been measured.
Gene: Protein-coding gene on chromosome 2 (72,942,036 to 73,075,619, reverse strand). Ensembl gene ENSG00000144040.
Subcellular location: Mitochondrion inner membrane
Subcellular location (Human Protein Atlas): Mitochondria; Nucleoplasm
Gene Ontology:
Molecular function: protein binding; citrate transmembrane transporter activity; monoatomic ion transmembrane transporter activity
Biological process: citrate transport; mitochondrial transmembrane transport; monoatomic ion transmembrane transport; monoatomic ion transport; positive regulation of cold-induced thermogenesis; transmembrane transport
Cellular component: mitochondrial inner membrane; mitochondrion; membrane
Genetic constraint (gnomAD): Loss-of-function variants: 42 observed, 47.33 expected, observed/expected ratio (o/e) 0.89, 90% interval 0.69 to 1.15. The upper end of that interval is the gene's LOEUF score, 1.15, which puts it in group 5 of 6, group 1 being the genes least tolerant of losing a copy. Missense variants: 462 observed, 443.9 expected, observed/expected ratio (o/e) 1.04, 90% interval 0.96 to 1.12. Synonymous variants: 203 observed, 183.78 expected, observed/expected ratio (o/e) 1.1, 90% interval 0.98 to 1.24.
Homologues: Orthologues: chimpanzee SFXN5 (100% identical), guinea pig SFXN5 (99% identical), dog SFXN5 (98% identical), rat Sfxn5 (98% identical), mouse Sfxn5 (97% identical), pig SFXN5 (88% identical), tropical clawed frog sfxn5 (81% identical), zebrafish sfxn5b (74% identical), zebrafish sfxn5a (70% identical), macaque SFXN5 (69% identical), Caenorhabditis elegans sfxn-5 (49% identical). Paralogues in human: SFXN2 (38% identical), SFXN1 (37% identical), SFXN3 (37% identical), SFXN4 (23% identical).
Diseases named in the same sentence as SFXN5 in open-access papers:
SFXN5 is named in the same sentence as 7 diseases in open-access papers, as found by Europe PMC text mining. Sharing a sentence is not in itself a finding about the gene and the disease. The quoted sentences say what the papers report.
anaphylaxis (1 paper, 2019). An acute hypersensitivity reaction that occurs from exposure to an allergen. "This approach identified several genes that are associated with aging (ATP2B2, CAV3, CNTN3, CTNNA2, GRID2), inflammation (ATP2B2, CAV3, RAD18, KBTBD8), vascular permeability (SFXN5, RAD18) and anaphylaxis (CAV3, RAD18, CTNNA2, ATP2B2 and GRID2)." (PMID 31701027, 2019).
interstitial lung disease (1 paper, 2023). A diverse group of lung diseases that affect the lung parenchyma. "Study on SFXN5 was rare, and the limited studies indicated that SFXN5 gene variation might be correlated with interstitial lung disease." (PMID 37786439, 2023).
pancreatic cancer (1 paper, 2023). "In the current study, a total of 17 genes with prognostic values have been identified, of which 8 genes (SFXN5, LRRC8E, KCNJ10, UPB1, SLC43A2, SLC38A10, ACCS, and SLC38A5) were identified for the first time in pancreatic cancer." (PMID 37333498, 2023).
prostatitis (1 paper, 2025). An infectious or non-infectious inflammatory process affecting the prostate gland. "SFXN5, a mitochondrial protein predicted to enable citrate transmembrane transporter activity, was identified as a prostatitis-related gene." (PMID 40919435, 2025). "Our analysis revealed two Tier 2 genes (NOA1 and ELAC2) for BPH, two Tier 3 genes (TRMU and SFXN5) for prostatitis, and six Tier 3 genes (MRPL24, NDUFS6, PUS1, NBR1, GLOD4, and PCBD2) for PCa." (PMID 40919435, 2025). "We revealed two Tier 2 genes (NOA1 and ELAC2) and one Tier 3 gene (ACAT1) for BPH, two Tier 3 genes (TRMU and SFXN5) for prostatitis, and six Tier 3 genes (MRPL24, NDUFS6, PUS1, NBR1, GLOD4, and PCBD2) for PCa." (PMID 40919435, 2025). "For prostatitis, TRMU and SFXN5 were identified as tier 3 genes, with TRMU emerging as a risk gene [eQTLGen: OR (95% CI) = 1.67 (1.29, 2.15), P-value = 8.96 × 10−5], and SFXN5 as a protective factor [eQTLGen: OR (95% CI) = 0.89 (0.80, 0.98), P-value = 0.02]." (PMID 40919435, 2025). "Understanding how SFXN5 modulates immune cell behavior and mitochondrial metabolism may therefore provide novel insights into prostatitis pathogenesis and uncover potential therapeutic targets aimed at mitigating inflammation." (PMID 40919435, 2025).
SFXN5 also shares sentences with these, for which no sentence is quoted: Alzheimer disease (1 paper); malakoplakia (1); tumor (1).